CCP110 (centriolar coiled-coil protein 110)
Description:
Necessary for centrosome duplication at different stages of procentriole formation. Acts as a key negative regulator of ciliogenesis in collaboration with CEP97 by capping the mother centriole thereby preventing cilia formation. Also involved in promoting ciliogenesis. May play a role in the assembly of the mother centriole subdistal appendages (SDA) thereby effecting the fusion of recycling endosomes to basal bodies during cilia formation (By similarity). Required for correct spindle formation and has a role in regulating cytokinesis and genome stability via cooperation with CALM1 and CETN2.
Synonyms: CP110; Cep110; KIAA0419
Tractability: PROTAC: UniProt records ubiquitination sites on it; ubiquitination databases record sites on it; its protein half-life has been measured.
Gene: Protein-coding gene on chromosome 16 (19,523,811 to 19,553,408, forward strand). Ensembl gene ENSG00000103540.
Subcellular location: Cytoplasm, cytoskeleton, microtubule organizing center, centrosome, centriole; Cytoplasm, cytoskeleton, microtubule organizing center, centrosome; Cytoplasm, cytoskeleton, cilium basal body
Subcellular location (Human Protein Atlas): Centriolar satellite
Pathways (Reactome):
Cell Cycle: AURKA Activation by TPX2; Loss of Nlp from mitotic centrosomes; Loss of proteins required for interphase microtubule organization from the centrosome; Recruitment of NuMA to mitotic centrosomes; Recruitment of mitotic centrosome proteins and complexes; Regulation of PLK1 Activity at G2/M Transition
Metabolism of proteins: Ub-specific processing proteases
Organelle biogenesis and maintenance: Anchoring of the basal body to the plasma membrane
Signal Transduction: RHOV GTPase cycle
Gene Ontology:
Molecular function: microtubule binding; protein binding
Biological process: centriole replication; centrosome duplication; negative regulation of cilium assembly; regulation of cytokinesis; ciliary basal body organization; positive regulation of cilium assembly
Cellular component: centriole; centrosome; protein-containing complex; cytosol; microtubule organizing center
Genetic constraint (gnomAD): Loss-of-function variants: 11 observed, 48.99 expected, observed/expected ratio (o/e) 0.22, 90% interval 0.14 to 0.37. The upper end of that interval is the gene's LOEUF score, 0.37, which puts it in group 1 of 6, group 1 being the genes least tolerant of losing a copy. Missense variants: 660 observed, 801.37 expected, observed/expected ratio (o/e) 0.82, 90% interval 0.77 to 0.88. Synonymous variants: 240 observed, 275.8 expected, observed/expected ratio (o/e) 0.87, 90% interval 0.78 to 0.97.
Homologues: Orthologues: chimpanzee CCP110 (97% identical), macaque CCP110 (94% identical), dog CCP110 (84% identical), pig CCP110 (81% identical), guinea pig CCP110 (79% identical), rabbit CCP110 (76% identical), rat Ccp110 (71% identical), mouse Ccp110 (70% identical), tropical clawed frog ccp110 (44% identical), zebrafish cp110 (15% identical), Drosophila melanogaster Cp110 (11% identical).
Diseases named in the same sentence as CCP110 in open-access papers:
CCP110 is named in the same sentence as 23 diseases in open-access papers, as found by Europe PMC text mining. Sharing a sentence is not in itself a finding about the gene and the disease. The quoted sentences say what the papers report.
dysplasia (1 paper, 2022). A usually neoplastic transformation of the cell, associated with altered architectural tissue patterns. "Interestingly, Ccp110 knockout mice (CP110 orthologue) present skeletal dysplasia resembling Jeune/SRPS." (PMID 35748595, 2022).
schizophrenia (1 paper, 2023). A major psychotic disorder characterized by abnormalities in the perception or expression of reality. "Studies have shown that centriolar coiled-coil protein 110 (CCP110), cytoskeleton-associated protein 5 (CKAP5), disrupted in schizophrenia 1 (DISC1), and transforming acidic coiled-coil containing protein 3 (TACC3) are essential for oocyte microtubule polymerization and spindle assembly." (PMID 37240406, 2023).
cardiac disease (1 paper, 2018). "The remaining differentially expressed genes in MuRF1 Tg + hearts after CH exposure associated with alternative splicing (Ptpru, Svopl, Syt16, Ccp110, Jakmip3, Kansl1l) have not been functionally defined in heart and/or cardiac disease to our knowledge." (PMID 30241514, 2018).
CCP110 also shares sentences with these, for which no sentence is quoted: breast carcinoma (4 papers); ciliopathy (4); lung carcinoma (3); cancer (2); Hydrocephalus (2); prostate carcinoma (2); tumor (2); Bardet-Biedl syndrome (1); chronic rhinosinusitis (1); epilepsy (1); leukemia (1); metastatic cancer (1); metastatic disease (1); metastatic prostate carcinoma (1); nasal polyps (1); ovarian carcinoma (1); prostate tumor (1); pulmonary arterial hypertension (1); short rib-polydactyly syndrome (1); virus infection (1).